IPO7 (importin 7)
Description:
Functions in nuclear protein import, either by acting as autonomous nuclear transport receptor or as an adapter-like protein in association with the importin-beta subunit KPNB1. Acting autonomously, is thought to serve itself as receptor for nuclear localization signals (NLS) and to promote translocation of import substrates through the nuclear pore complex (NPC) by an energy requiring, Ran-dependent mechanism. At the nucleoplasmic side of the NPC, Ran binds to importin, the importin/substrate complex dissociates and importin is re-exported from the nucleus to the cytoplasm where GTP hydrolysis releases Ran. The directionality of nuclear import is thought to be conferred by an asymmetric distribution of the GTP- and GDP-bound forms of Ran between the cytoplasm and nucleus. Mediates autonomously the nuclear import of ribosomal proteins RPL23A, RPS7 and RPL5. In association with KPNB1 mediates the nuclear import of H1 histone and the Ran-binding site of IPO7 is not required but synergizes with that of KPNB1 in importin/substrate complex dissociation. Promotes odontoblast differentiation via promoting nuclear translocation of DLX3, KLF4, SMAD2, thereby facilitating the transcription of target genes that play a role in odontoblast differentiation (By similarity). Facilitates BMP4-induced translocation of SMAD1 to the nucleus and recruitment to the MSX1 gene promoter, thereby promotes the expression of the odontogenic regulator MSX1 in dental mesenchymal cells (By similarity). Also promotes odontoblast differentiation by facilitating the nuclear translocation of HDAC6 and subsequent repression of RUNX2 expression (By similarity). Inhibits osteoblast differentiation by inhibiting nuclear translocation of RUNX2 and therefore inhibition of RUNX2 target gene transcription (By similarity). In vitro, mediates nuclear import of H2A, H2B, H3 and H4 histones. (Microbial infection) Mediates the nuclear import of HIV-1 reverse transcription complex (RTC) integrase. Binds and mediates the nuclear import of HIV-1 Rev.
Synonyms: Imp7; RanBP7
Tractability: PROTAC: ubiquitination databases record sites on it; its protein half-life has been measured.
Gene: Protein-coding gene on chromosome 11 (9,384,626 to 9,448,127, forward strand). Ensembl gene ENSG00000205339.
Subcellular location: Cytoplasm; Nucleus
Subcellular location (Human Protein Atlas): Cytosol; Nucleoplasm
Pathways (Reactome):
Disease: Maturation of DENV proteins
Gene Ontology:
Molecular function: protein binding; SMAD binding; GTPase regulator activity; nuclear import signal receptor activity; small GTPase binding; histone binding
Biological process: negative regulation of cell cycle; negative regulation of osteoblast differentiation; positive regulation of odontoblast differentiation; positive regulation of protein localization to nucleus; protein import into nucleus; intracellular protein transport
Cellular component: cytosol; membrane; nucleoplasm; cytoplasm; nuclear envelope; nuclear pore; nucleus
Genetic constraint (gnomAD): Loss-of-function variants: 2 observed, 45.76 expected, observed/expected ratio (o/e) 0.0437, 90% interval 0.017 to 0.14. The upper end of that interval is the gene's LOEUF score, 0.14, which puts it in group 1 of 6, group 1 being the genes least tolerant of losing a copy. Missense variants: 338 observed, 511.39 expected, observed/expected ratio (o/e) 0.66, 90% interval 0.6 to 0.72. Synonymous variants: 171 observed, 176.79 expected, observed/expected ratio (o/e) 0.97, 90% interval 0.85 to 1.1.
Homologues: Orthologues: dog IPO7 (100% identical), macaque IPO7 (100% identical), chimpanzee IPO7 (99% identical), guinea pig IPO7 (99% identical), rabbit IPO7 (99% identical), rat Ipo7 (99% identical), pig IPO7 (99% identical), mouse Ipo7 (99% identical), tropical clawed frog ipo7 (93% identical), zebrafish ipo7 (85% identical), Drosophila melanogaster msk (55% identical). Paralogues in human: IPO8 (64% identical), CSE1L (20% identical), IPO9 (18% identical), IPO11 (15% identical).
Diseases named in the same sentence as IPO7 in open-access papers:
IPO7 is named in the same sentence as 38 diseases in open-access papers, as found by Europe PMC text mining. Sharing a sentence is not in itself a finding about the gene and the disease. The quoted sentences say what the papers report.
pancreatic cancer (7 papers, 2020 to 2025). "In the present study, we found that IPO7 expression in pancreatic cancer tissues was markedly elevated, and its overexpression was significantly associated with shorter survival of pancreatic cancer patients." (PMID 34660566, 2021). "This work is performed to probe the role of IPO7 in pancreatic cancer development and its potential downstream mechanisms." (PMID 35588577, 2022). "•IPO7 remarkably enhanced pancreatic cancer cell proliferation, migration and invasion and suppressed apoptosis." (PMID 35588577, 2022). "The statistical results showed that IPO7 positive rate in pancreatic cancer tissues was markedly higher than that in the adjacent tissues." (PMID 34660566, 2021). "The present research revealed that IPO7 was significantly upregulated in pancreatic cancer, and it markedly facilitated the proliferation, migration, and invasion of pancreatic cancer cells." (PMID 34660566, 2021). "In the present work, our data suggested that IPO7 positively regulated MALAT1 expression in pancreatic cancer." (PMID 34660566, 2021). "In the present work, it was confirmed that MALAT1 was positively regulated by IPO7 in pancreatic cancer cells." (PMID 34660566, 2021). "•IPO7 facilitated the malignant phenotype of pancreatic cancer cells by up-regulating ERBB2." (PMID 35588577, 2022). "Besides, qPCR and Western blot suggested that IPO7 expression was remarkably enhanced in pancreatic cancer tissues and cell lines at mRNA and protein levels compared with normal tissues and cells." (PMID 34660566, 2021). "For further expounding the molecular mechanism of IPO7 in regulating pancreatic cancer progression, StarBase and DIANA LncBase Predicted v.2 were performed to explore the miRNAs that potentially interacted with MALAT1, and miR-129-5p was among the candidate miRNAs." (PMID 34660566, 2021).
pancreatic cancer (continued). "Collectively, these data suggested that IPO7 promoted pancreatic cancer progression." (PMID 34660566, 2021). "Furthermore, miR-129-5p was identified as a posttranscriptional regulator for IPO7, and its inhibition led to IPO7 overexpression in pancreatic cancer cells." (PMID 34660566, 2021). "Additionally, hematoxylin and eosin staining indicated that the knockdown of IPO7 reduced lung metastasis of pancreatic cancer cells." (PMID 34660566, 2021). "Overexpression of IPO7 facilitated the malignant phenotypes of pancreatic cancer cells." (PMID 34660566, 2021). "Additionally, we detected IPO7 expression in carcinoma tissues and adjacent tissues of 55 patients with pancreatic cancer by IHC." (PMID 34660566, 2021). "IPO7 was found to be upregulated in several pancreatic cancer lines (Suit2 and MIA PaCa2)." (PMID 33584809, 2020). "Studies in cervical and pancreatic cancers indicate that elevated IPO7 expression correlates with poor prognosis and decreased CD8 T cell infiltration in cervical cancer and adverse outcomes in pancreatic cancer patients." (PMID 38786019, 2024).
chronic myelogenous leukemia (3 papers, 2019 to 2021). "In addition, curcumin increases miR-22 that directly targets IPO7 in chronic myelogenous leukemia cells, indicating that curcumin modulates HIF-1α activity via the miR-22/IPO7 axis." (PMID 34575983, 2021). "Furthermore, our group previously demonstrated that IPO7 is responsible for HIF-1α nuclear translocation in chronic myelogenous leukemia cells." (PMID 30781795, 2019).
glioblastoma (3 papers, 2016 to 2022). The most malignant astrocytic tumor (WHO grade IV). "Reportedly, IPO7 is carcinogenic in several human malignancies, such as colorectal cancer and glioblastoma." (PMID 35588577, 2022). "Previous studies have indicated that IPO7 promoted glioblastoma cell proliferation and migration by increasing the nuclear import of GLI1." (PMID 34650978, 2021). "Last, FOXM1 stimulates self-renewal, tumorigenicity and invasiveness of glioblastoma stem-like cells by transactivating a number of molecules, including IPO7 (importing-7), CDC20, PDGF-A, ANXA1, MMP-2 and VEGF." (PMID 27259253, 2016). "Moreover, Forkhead box M1 (FOXM1) transcriptionally activates the expression of IPO7 to promote the nuclear import of glioma-associated oncogene homolog 1 (GLI1), and this biological process modulates the growth, migration, and invasion of glioblastoma multiforme cells in vitro." (PMID 35588577, 2022).
HIV-1 infection (3 papers, 2006 to 2009). The type species of lentivirus and the etiologic agent of acquired immunodeficiency syndrome (AIDS). "Using this approach we have recently found that importin 7 (imp7) stimulates nuclear import of HIV-1 RTCs and that siRNA-mediated depletion of imp7 inhibits HIV-1 infection, though only by a few fold." (PMID 17067381, 2006).
viral infection (3 papers, 2011 to 2025). "Seven of these acetylated proteins, including DDX3X, PTBD, TRIM56, IPO7, PPID, SHMT2, and ZC3HAV1, have been implicated in innate immunity and viral infection, based on functional annotation using databases such as GO Biological Process, KEGG and reactome." (PMID 39747662, 2025). "Regarding viral infection and replication, IPO7 has been reported to regulate viral proteins, such as HIV-1 integrase or purified intracellular reverse transcription complex, and inhibit virus replication." (PMID 39146232, 2024).
breast carcinoma (2 papers, 2023 to 2024). "IPO7 expression is elevated in breast cancer and is associated with poorer patient survival and IPO7 expression inhibition promotes the drug sensitivity of triple-negative breast cancer cells." (PMID 39353922, 2024).
cervical cancer (2 papers, 2021 to 2024). A primary or metastatic malignant neoplasm involving the cervix. "Intriguingly, we found that the IPO7 expression was negatively correlated with CD8 T cell infiltration via regulating the expression of CD276 in cervical cancer." (PMID 34650978, 2021). "To further evaluate the expression of IPO7 in cervical cancer (CC), we initially investigated the gene expression profiles from the GSE6791 and GSE7803 datasets." (PMID 34650978, 2021). "Moreover, IPO7 contributed to activating the PI3K/AKT-mTOR pathway by mediating the nuclear import of GTF2I in cervical cancer cells." (PMID 34650978, 2021). "The results of a negative correlation between the IPO7 and CD8 T cell infiltration indicate that the IPO7 might play an important impact on the immune microenvironment of cervical cancer." (PMID 34650978, 2021).
colorectal cancer (2 papers, 2020 to 2021). A primary or metastatic malignant neoplasm that affects the colon or rectum. "Importin 7 (IPO7) performs a role in nuclear protein import and is overexpressed in cancers, including lung and colorectal cancer." (PMID 34575983, 2021).
prostate carcinoma (2 papers, 2017 to 2022). A carcinoma that arises from epithelial cells of the prostate gland. "The protein level of IPO7 is up-modulated in primary prostate cancer cells and can participate in modulating the proliferation of cancer cells." (PMID 35588577, 2022).
amyloidosis (1 paper, 2024). A disorder characterized by the localized or diffuse accumulation of amyloid protein in various anatomic sites. "In addition, nuclear transport proteins, including RAN GTAPase-activating protein 1, importin-7 and importin-5, have been reported to be upregulated in the hippocampus of AppNL-F mice before the onset of amyloidosis." (PMID 38612434, 2024).
asthma (1 paper, 2020). "Others have found that the expression level of IPO7 is related to the clinical symptoms of human asthma." (PMID 32609751, 2020).
Burkitt lymphoma (1 paper, 2021). A rare form of malignant mature B-cell non-Hodgkin lymphoma. "For example, we have evicted EBV from Burkitt Lymphoma cells and found that their levels of the IPO7 protein increased." (PMID 33664726, 2021).
ependymal tumor (1 paper, 2020). A group of neoplasms which arise from the ependymal lining of the cerebral ventricles and from the remnants of the central canal of the spinal cord.
gastric carcinoma (1 paper, 2021). A carcinoma that arises from epithelial cells of the stomach. "We first attempted to delete the IPO7 gene from the EBV-negative 293T cell line, from an EBV-positive B-cell line, 721, and from an EBV-positive gastric carcinoma cell line, SNU-719 using CRISPR/Cas9." (PMID 33664726, 2021). "In addition, decreasing the expression of IPO7 in these cells did not affect their proliferation, while increasing it in EBV-positive gastric carcinoma cells inhibited their growth." (PMID 33664726, 2021).
hepatocellular carcinoma (1 paper, 2022). A malignant tumor that arises from hepatocytes. "ABCB6, IPO7, TIMM9, FZD7, and ACAT1, the five HBV-related genes that affect the prognosis, can work as reliable biomarkers for the diagnosis of Hepatocellular carcinoma, giving a new insight for improving the prognosis, diagnosis, and treatment outcomes of HBV-type Hepatocellular carcinoma." (PMID 36685852, 2022).
invasive breast carcinoma (1 paper, 2024). A carcinoma that infiltrates the breast parenchyma. "Two of the top interactors identified in all three pulldowns, ANXA2 and IPO7 are also implicated in invasive breast cancers." (PMID 39353922, 2024).
Listeria monocytogenes infection (1 paper, 2020). "Interestingly, cells silenced for IPO7 or all three importins did not undergo H3K18 deacetylation suggesting that IPO7 is specifically required to allow SIRT2 to carry out nuclear functions in response to Listeria monocytogenes infection." (PMID 32042025, 2020).
nasopharyngeal carcinoma (1 paper, 2024). A carcinoma arising from the nasopharyngeal epithelium.
ovarian carcinoma (1 paper, 2010). A malignant neoplasm originating from the surface ovarian epithelium. "Moreover, the ovarian cancer cells typically had higher transcript levels of importin 7 (Imp7) and importin B1 (ImpB1, also known as KPNB1), members of the karyopherin/importin-beta family of nuclear transport factors that have been shown in Drosophila to modulate MAPK/ERK nuclear localization." (PMID 20174585, 2010).
papillary thyroid cancer (1 paper, 2025).
thyroid (1 paper, 2025).
thyroid tumor (1 paper, 2025). A benign or malignant neoplasm affecting the thyroid gland. "This profile of IPO7 and miR-7-5p regulation, which is consistent across high-risk (PTC) and low-risk (NIFTP) neoplasms, suggests that upregulation of IPO7 and downregulation of miR-7-5p are involved in neoplastic transformation rather than in the progression of thyroid tumors." (PMID 40565276, 2025).